VIM (vimentin)
Diseases named in the same sentence as VIM in open-access papers (continued):
Sharing a sentence is not in itself a finding about the gene and the disease.
cancer (continued). "SATB1 seemed to promote the mesenchymal phenotype of cancer cells by upregulating Vimentin and N-cadherin, as well as downregulating the key epidermal markers Claudin-1, β-catenin and E-cadherin;." (PMID 31450715, 2019). "In line with RNA-seq and Go analysis, Western blot analysis validated these changes in gene expression, and revealed a moderate increase of E-cadherin and/or decrease of Vimentin in USP22−/− cancer cells that reflects suppression of EMT singaling pathway." (PMID 31842906, 2019). "The overall expression of Vimentin was significantly higher in cancer tissues than in adjacent normal tissues (p < 0.01)." (PMID 31420013, 2019). "Simultaneously, the expression of metastatic markers, such as Slug, Twist1 and vimentin, in primary cells derived from the malignant tumors, was higher than in metastatic nodules." (PMID 31450740, 2019). "Vimentin, a protein which is a target of many PTMs including sumoylation, O’glcNAc and citrullination has recently gained attention due to its involvement in cancer." (PMID 31827725, 2019). "The garlic-derived phytochemical ajoene targets and covalently modifies vimentin in cancer cells by S-thiolating Cys-328." (PMID 30894168, 2019). "Studies also showed that EMT is an initial step in cancer metastasis, and the major cytoskeletal protein vimentin, which is a positive regulator and a canonical marker of EMT, is correlated with aggressive clinical phenotype in TNBC." (PMID 31186039, 2019). "We measured differential expression of the epithelial marker, E-Cadherin, and mesenchymal markers including vimentin, N-Cadherin, and snail to check the cancer stem cell properties of tumorspheres." (PMID 30915120, 2019). "The immunoprofile indicated unfavorable prognosis for mesenchymal-type carcinomas (negativity for E-cadherin and positivity for vimentin, with membrane to nuclear translocation or negativity of β-catenin)." (PMID 31205468, 2019). "Vimentin positive dedifferentiated-poorly cohesive carcinomas should be considered as mesenchymal-type highly malignant carcinomas." (PMID 31205468, 2019). "Vimentin-positive carcinoma cells were randomly scattered among the cells with epithelial connections." (PMID 30649642, 2019). "Carcinoma cells admixed with CAFs showed stronger E-cad, vimentin, and fibronectin staining as well as nuclear ZEB1 staining than did those comingled with/without control fibroblasts." (PMID 31331982, 2019). "Consistently, collagen I-induced upregulation of proliferation (PCNA), phosphorylated ERK1/2, EMT (vimentin and N-cadherin), cancer stem cell marker Nanog was markedly reduced in heat-exposed residual HCC cells pretreated with ERK1/2 inhibitor U0126." (PMID 30227844, 2018). "Previously, we showed that ZEB2 cooperates with the transcription factor Sp1 to function as a transcriptional activator of vimentin, integrin α5, and cadherin-11, which promotes cancer cell invasion." (PMID 29416649, 2018). "Expression of vimentin, which is an important constituent of the cytoskeleton, goes up in many types of cancer during EMT and in the stromal cells of several cancers." (PMID 29681769, 2018). "Our strategy can also significantly inhibit cancer migration and invasion, associated with altered expression of MMP-2/− 9, E-cadherin, vimentin and snail." (PMID 29587668, 2018). "Concomitant with EMT, an increase in motility, migratory and invasive properties and in expression levels of EMT markers such as N-Cadherin, Fibronectin and Vimentin, take place which results in the increase in metastasis potential of cancer cells." (PMID 29743493, 2018). "Many different types of cells contain vimentin and a lot of it is found in cancer cells that have spread beyond their original location to other sites in the body." (PMID 29513221, 2018). "Twist, vimentin, fascin, Mad, Brk, Tsk5, Rab40B, ERK1/2 and PLCγ are associated with bulk cancer cell migration." (PMID 29976164, 2018).
cancer (continued). "Vimentin plays a vital role in the progression and prognosis of cancer via the EMT and the corresponding signaling pathways, which contributes to the tumorigenesis, metastasis, invasion, and therapeutic resistance of various tumors." (PMID 29955607, 2018). "The accumulated evidence has indicated the diagnostic role of cytokeratin (CK) and vimentin protein immunoassay in primary esophageal spindle cell carcinoma (PESC), which is a rare malignant tumor with epithelial and spindle components." (PMID 29609569, 2018). "During EMT, cancer cells gain mesenchymal cell markers, such as vimentin, α-smooth muscle actin (SMA), fibronectin, N-cadherin, etc.." (PMID 29738439, 2018). "Given that vimentin regulates cell migration and adhesion, which are crucial processes in cancer progression, it has long been seen as a factor in cancer progression." (PMID 29925392, 2018). "Fibroblasts that promote the growth of cancer cells in vivo have also been shown to have reorganised vimentin filaments, compared to normal fibroblasts." (PMID 30248895, 2018). "Intriguingly, both liprin-α1 and vimentin have important roles in invadosome function in cancer cells, vimentin being important in stabilizing and in elongation of mature invadopodia." (PMID 30005669, 2018). "The combination of FIS and PTX significantly reduced cancer cell migration and invasion, at least partially, through a marked rearrangement of actin and vimentin cytoskeleton and the modulation of metastasis-related genes." (PMID 29495431, 2018). "It was also noteworthy that vimentin expression was very high in PANC-1 cancer cells grown in 3D spheroids and further increase was observed upon PSC co-culture." (PMID 29329547, 2018). "E-cadherin functions as an invasion suppressor; whereas Slug and Vimentin promote cell motility and invasion in cancers." (PMID 29610526, 2018). "Molecularly, the observed inclination towards the cancer stem-like properties was associated with the increased expression level of Notch1, WNT1 (both markers of stemness), NF-κB and Vimentin." (PMID 30005681, 2018). "Vimentin expression is elevated in cancer development and progression, as demonstrated by multiple recent studies usingin vivo cancer metastasis models." (PMID 30505430, 2018). "Vimentin is an intermediate-sized filament that is highly expressed in mesenchymal cells and is generally used to identify cancer cells proceeding EMT based on a positive correlation of vimentin expression with increased invasiveness and metastasis." (PMID 30181714, 2018). "Zeb1 is a well-known EMT master regulator that induces mesenchymal properties in cancer cells by increasing N-cadherin and Vimentin levels making it more invasive and metastatic." (PMID 30483264, 2018). "Near-adjacent sections were stained for smooth muscle actin and vimentin to detect reactive stroma and with pan cytokeratin antibodies to detect epithelial/cancer cells." (PMID 29858602, 2018). "A growing number of evidence has established that miRNAs affect cancer development by regulating vimentin." (PMID 30181714, 2018). "Vimentin IFs are required for the plasticity of mesenchymal cells under normal physiological conditions and for the migration of cancer cells that have undergone epithelial–mesenchymal transition." (PMID 30505430, 2018). "Immunohistochemistry (IHC) and immunofluorescence staining for CD133 as well as other cancer-associated proteins, including cytokeratin 19, TGF-β1, p-Smad2 and epithelial–mesenchymal transition (EMT) markers S100A4, E-Cadherin and Vimentin were analyzed." (PMID 29510695, 2018). "Increasing studies investigated the prognostic roles of vimentin expression and its clinicopathological significance in cancer." (PMID 29955607, 2018).
cancer (continued). "Due to its overexpression in many kinds of cancers and its function in tumorigenic events, vimentin is an appealing drug target for cancer therapies." (PMID 30248895, 2018). "As a recognized EMT-associated molecule, miR-506 has been reported to be expressed in many types of cancer and to regulate EMT-associated genes, such as Snail2, Vimentin, and ETS-127,49,50." (PMID 30154460, 2018). "Here, we demonstrated that paclitaxel when combined with fisetin significantly reduced cancer cell migration and invasion, at least partially, through a marked rearrangement of actin and vimentin cytoskeleton and the modulation of metastasis-related genes." (PMID 29495431, 2018). "Previous studies also showed that inhibition of vimentin’s activity or suppression of its expression induce cancer-cell apoptosis and inhibit the invasion, motility and migration of cancer cells." (PMID 30440021, 2018). "Our results also suggest that Nup88 affects vimentin organization by altering its phosphorylation status, which contributes to cancer malignancy." (PMID 29724197, 2018). "The specific regulation of vimentin organization during cancer development has remained unclear even though vimentin expression is correlated with malignant transformation of cancer." (PMID 29724197, 2018). "In line with this, we demonstrate that the rVAR2-enriched CTC population from cancer patients contains vimentin-positive cells as well as EpCAM-negative cells, indicating that the rVAR2 isolates include mesenchymal-like subpopulations." (PMID 30115931, 2018). "Further, the cancer cells in the mixed model showed a more elongated cell morphology than those in the layer models, and also had distinct E-cadherin, fibronectin, and vimentin profiles, representing the EMT." (PMID 29370123, 2018). "IL-6/JAK/STAT3 pathway was shown to activate EMT through upregulation of Twist, N-cadherin and Vimentin in some types of cancer." (PMID 29581838, 2018). "Because of the significantly prognostic role of vimentin, researchers focused on its effect on the treatment of cancer." (PMID 29955607, 2018). "Vimentin is an intermediate filament expressed by mesenchymal cells and carcinoma cells that have undergone EMT, which is involved in the regulation of cell motility and invasion." (PMID 30275505, 2018). "In EMT, the exchange of cytokeratin for vimentin is explained by the fact that vimentin gives carcinoma cells more flexibility to change cell shape and thus adapt for migration better." (PMID 29976164, 2018). "Vimentin and Slug are mesenchymal-related proteins that promote migratory and invasive properties of carcinoma cells." (PMID 29535419, 2018). "Dysregulation of EMT markers, such as E-cadherin downregulation and N-cadherin and vimentin upregulation, promotes cancer cell invasion and migration." (PMID 29228592, 2017). "In this study, we found that p62 binds to vimentin and regulates vim entin protein level, which in turn contributes to cancer cell invasion and metastasis." (PMID 28968743, 2017). "We suggest that bigger NANOG-and vimentin-positive round cells with large nuclei that separated from surface epithelium represent putative cancer stem cells (CSCs) which arise in the EMT process." (PMID 28231820, 2017). "In a xenograft model of lung adenocarcinoma, injection of cancer cells that stably overexpress IL‐6 leads to the formation of tumors with EMT characteristics (E‐cadherin loss and vimentin expression) and in an increased number of lung metastases." (PMID 28599100, 2017). "Due to its elevated expression in most cancers, it is very essential to determine the role of vimentin in cancers including that of the breast." (PMID 28616237, 2017).
cancer (continued). "Subsequently, other biomarkers are also change involved in EMT, including N-cadherin, fibronectin, and vimentin, leading to cancer cell migration and invasion." (PMID 27966445, 2017). "Immunohistochemical double-staining of CD31 and vimentin on lung sections was performed to visualize endothelial cells and cancer cells." (PMID 27911269, 2017). "According to the results of our immunofluorescence double staining experiments in cancer cell lines treated with IL-6 or AG490, we found that p-STAT3 activation is more closely linked with vimentin expression than VE-cadherin expression." (PMID 29333928, 2017). "Next, we performed the microfluidic assay to verify the effect of vimentin on p62-mediated cancer cells invasion." (PMID 28968743, 2017). "When EMT occurs, cancer cells exhibited the decrease of cellular adhesion protein E-cadherin, and the increase of mesenchymal biomarkers N-cadherin, Snail and vimentin." (PMID 29190936, 2017). "A small subpopulation of cancer cells acquires cancer stem-like cell (CSCs) traits, exhibiting mesenchymal cell features associated with increase of EMT-related markers such us N-cadherin, Vimentin, α-SMA (anti alfa-smooth muscle actin), fibronectin or Snail." (PMID 29179450, 2017). "Vimentin and N-Cadherin are classic markers of this mesenchymal phenotype and are used to identify cancer tissues undergoing EMT." (PMID 28388562, 2017). "β-catenin re-localization at the cell surface of U94+ cancer cells together with a generally reduced cytoplasmic expression of vimentin was highly suggestive of MET." (PMID 28562350, 2017). "Following periostin treatment, qRT-PCR and Western blot analysis revealed induction of the EMT process by a shift in expression of cancer cells from epithelial (E-cadherin) to mesenchymal phenotypes (N-cadherin, vimentin, and Twist)." (PMID 28977942, 2017). "E-Cadherin, Vimentin, ZEB1, and N-Cadherin were introduced as the indicators in cancer progression, and their fluctuations were associated with the E2F3 and HIF-2α change." (PMID 28903320, 2017). "Since EMT was characterized by cancer cell migration and invasion, we detected the expression level of E-cadherin and Vimentin in cells with control or RUNX3 plasmids or control siRNA or RUNX3 siRNA." (PMID 28977878, 2017). "Gene set enrichment analysis revealed regulation of several hallmark cancer pathways, particularly of epithelial-to-mesenchymal transition (EMT), with VIM being the most significantly regulated gene." (PMID 29228717, 2017). "Resistant cancer cells have shown an increased expression of vimentin, suggesting that these cells have undergone to EMT." (PMID 28416737, 2017). "Epithelial to mesenchymal transition (EMT) generally precedes increased migration of cancer cells during which epithelial marker E-cadherin is downregulated with a concomitant upregulation of mesenchymal markers, snail and vimentin." (PMID 28418896, 2017). "TGF-b induces migration of cancer cells by activating N-Cadherin and inducing Twist and vimentin with consequent morphological cell changes." (PMID 28873435, 2017). "Meanwhile, the abnormal expression of MMP-9, MMP-2, vimentin and CD44v6 in cancer cells would lead to decreased adhesion, enhanced migration and invasion." (PMID 28774312, 2017). "In classical EMT, cancer cells undergoing EMT present a loss of epithelial markers (E-cadherin, etc.)and a gain of mesenchymal cell markers (Vimentin, etc.)." (PMID 28416770, 2017). "As the expression of epithelial markers (e.g. E-cadherin) and mesenchymal markers (e.g. fibronectin, N-cadherin, vimentin) are important indicators of cancer metastasis, Western blotting was employed to detect the EMT marker proteins expressions." (PMID 28931826, 2017). "Induction of EMT was associated with decreased AGR2 along with changes in cellular morphology, actin reorganization, inhibition of E-cadherin and induction of the mesenchymal markers vimentin and N-cadherin in various cancer cell lines." (PMID 28810836, 2017).
cancer (continued). "We also observed changes in the levels of proteins such as vimentin that impart invasive characteristics to the cancer cells." (PMID 28360821, 2017). "Our study found the K5/K14 pair to be a novel indirect target of vimentin, through which it is able to confer a dedifferentiated phenotype to the cancer cell." (PMID 28225793, 2017). "Epithelial-mesenchymal transition (EMT) is an essential early step in cancer metastasis, and E-cadherin and Vimentin are usually used as EMT markers." (PMID 28977933, 2017). "Collectively, these results suggest that vimentin is involved in maintaining a more dedifferentiated state of the cancer cell, perhaps through modulation of K5/K14 expression." (PMID 28225793, 2017). "The functions of some Annexin A1-associated proteins, such as the proteins which involved in cytoskeletal organization (Annexin A1, Vimentin, α-actinin 2, etc.)and vesicle transport, were closely related to the invasion and metastasis of malignant tumors." (PMID 28355254, 2017). "As other study shows, Akt activation induces cancer cell invasiveness partially through interaction with vimentin." (PMID 28126034, 2017). "Epithelial–mesenchymal transition (EMT), the main regulators of which are E-Cadherin, Fibronectin, Vimentin, and β-Catenin, is a key step in the initiation of cancer metastasis." (PMID 28427240, 2017). "Overexpression of vimentin is seen in various carcinomas like prostate, gastrointestinal, breast, lung and also melanomas." (PMID 28225793, 2017). "We used cytokeratin and vimentin staining to identify the carcinoma cells and the surrounding mesenchymal stroma, respectively (first string from the top)." (PMID 28903357, 2017). "The positive expression rates of vimentin were 52% (22/42) in carcinoma cells and 100% (42/42) in sarcomatoid cell (P = 0.000)." (PMID 28449664, 2017). "Vimentin is an intermediate filament protein, predominantly expressed in cells of mesenchymal origin, although its aberrant expression is seen in many carcinomas during epithelial mesenchymal transition." (PMID 28225793, 2017). "There were 12 cases in this study detected with positive vimentin staining not only in liver blood sinus but also in carcinoma cells." (PMID 27705934, 2017). "Double immunofluorescence staining further showed that B7-H4 is coexpressed with EMT-related markers, such as p-Smad2/3, Snail and Vimentin, in carcinoma cells." (PMID 29190910, 2017). "To study this phenomenon further we performed western blotting, immunofluorescence or RT-PCR for expression of keratin K5, often lost in aggressive carcinomas, keratin K8 and vimentin, often gained in aggressive carcinomas." (PMID 28661481, 2017). "Hypoxia gradually reduced SCEL expression in cancer cells, while the levels of vimentin and Lgr5 were increased and the epithelial marker E-cadherin was reduced." (PMID 27013588, 2016). "DcR3 overexpression significantly increased vimentin and N-cadherin expression and decreased E-cadherin expression both in vitro and in vivo—findings consistent with those of EMTs observed in cancer cells." (PMID 27764793, 2016). "Butyrate/HDACi‐resistant CRC cells differ from their butyrate/HDACi‐sensitive counterparts in the expression of many genes, including the gene encoding vimentin (VIM) that is usually expressed in normal mesenchymal cells and is involved in cancer metastasis." (PMID 27072512, 2016). "Second, vimentin intermediate filaments (IF) cooperate with actin and microtubules for the elongation of protrusions in invasive cancer cells, which is useful to understand the morphological changes observed in CEEMs." (PMID 27602764, 2016). "Silencing of vimentin induced upregulation of cancer stem cell markers and both A2780-DR and A2780-VIM-KN cells were more facile to form spheroids than control cells under serum-free culture condition." (PMID 27322682, 2016).